RNU6-1180P (RNA, U6 small nuclear 1180, pseudogene)
Gene: Small nuclear RNA gene on chromosome 2 (113,086,805 to 113,086,911, forward strand). Ensembl gene ENSG00000201805.
Homologues: Orthologues: chimpanzee U6 (100% identical), guinea pig U6 (85% identical), mouse Gm26468 (76% identical), mouse Gm23275 (72% identical), pig U6 (72% identical), rat LOC120101209 (72% identical). Paralogues in human: RNU6-38P (88% identical), RNU6-11P (87% identical), RNU6-37P (87% identical), RNU6-1331P (86% identical), RNU6-23P (86% identical), RNU6-242P (86% identical), RNU6-25P (86% identical), RNU6-445P (86% identical), RNU6-574P (86% identical), RNU6-1 (85% identical), RNU6-1094P (85% identical), RNU6-2 (85% identical), and 1284 more.